EIF2S2P3 (eukaryotic translation initiation factor 2 subunit 2 beta pseudogene 3)
Gene: Processed pseudogene on chromosome 10 (92,668,745 to 92,669,743, reverse strand). Ensembl gene ENSG00000236493.
Diseases named in the same sentence as EIF2S2P3 in open-access papers:
EIF2S2P3 is named in the same sentence as 2 diseases in open-access papers, as found by Europe PMC text mining. Sharing a sentence is not in itself a finding about the gene and the disease.
EIF2S2P3 shares sentences with these, for which no sentence is quoted: dementia (1 paper); depression (1).